DPP4 (dipeptidyl peptidase 4)
Diseases named in the same sentence as DPP4 in open-access papers (continued):
Sharing a sentence is not in itself a finding about the gene and the disease.
type 2 diabetes (continued). "CKD denotes chronic kidney disease; T2D, type 2 diabetes; SD, standard deviation; SGLT2, sodium glucose transport-2; RAS, renin-angiotensin system; MRA, mineral corticoid antagonists; DPP-4, Dipeptidyl peptidase-4; GLP-1, glucagon-like peptide-1." (PMID 40676552, 2025). "This study examines DKA signals in type 2 diabetes, focusing on sodium–glucose cotransporter-2 (SGLT2) inhibitors, glucagon-like peptide-1 (GLP-1) receptor agonists, and dipeptidyl-peptidase-4 (DPP-4) inhibitors." (PMID 40006028, 2025). "Sitagliptin (SITA), a dipeptidyl peptidase-4 (DPP-4) inhibitor, is a widely used drug for managing Type 2 diabetes by increasing the levels of incretin hormones, which promote insulin secretion." (PMID 40136627, 2025). "Several patients were also on insulin, sulfonylureas, dipeptidyl peptidase 4 (DPP-4) inhibitors, and SGLT2 inhibitors, reflecting the progressive and multifaceted treatment needs of type 2 diabetes." (PMID 41018312, 2025). "Dipeptidyl-peptidase 4 (DPP4)/CD26 inhibitors (gliptins), a class of hypoglycemic drugs, are currently registered in many countries for the treatment of type 2 diabetes." (PMID 40246828, 2025). "Both DPP-4 and SGLT2 inhibitors have been selected as the first choice for type 2 diabetes in Japanese clinical practice, and they are appropriate active comparators in the Japanese context." (PMID 41041642, 2025). "Dipeptidyl peptidase-4 (DPP-4) inhibitors and glucagon-like peptide-1 (GLP-1) receptor agonists (RAs) are important treatments for type 2 diabetes." (PMID 40385831, 2025). "The effect of incretins on potentiating insulin secretion is clinically used for the treatment of type 2 diabetes, such as GLP-1 analogues and DPP4 inhibitors which inhibit GLP-1 inactivating enzyme, DPP4." (PMID 40317718, 2025). "According to Brunton, treatment for MetS and type 2 diabetes has been transformed by synthetic GLP-1 receptor agonists (like liraglutide and semaglutide) and DPP-4 inhibitors (like sitagliptin)." (PMID 41300521, 2025). "We chose Sitagliptin because it has a high specificity against DPP4 and was the first DPP4 inhibitor approved by the Food and Drug Administration (FDA) for use in type 2 diabetes in 2006 with successful use in patients since." (PMID 40825831, 2025). "GLP-1 receptor agonists and dipeptidyl peptidase-4 (DPP4) inhibitors, which prevent the degradation of endogenous GLP-1, are widely used in the treatment of type 2 diabetes." (PMID 40806500, 2025). "Nevertheless, other authors reported that for type 2 diabetes patients which are administered DPP-4 inhibitors, these medications ineffectively prevent P. gingivalis DPP-4 from entering the circulation." (PMID 38337597, 2024). "Current treatment for the management of type 2 diabetes includes lifestyle changes and medications including metformin, sulfonylureas, glinides, thiazolidinediones, GLP-1 agonists, DPP-4 inhibitors, SGLT-2 inhibitors, and insulin analogs." (PMID 39149678, 2024). "This study aims to investigate the changes in circulating dipeptidyl peptidase-4 (DPP-4) activity following short-term intensive insulin therapy (SIIT) in newly diagnosed type 2 diabetes (T2D) patients and to assess its potential in predicting long-term remission." (PMID 38476668, 2024). "Intriguingly, a large-scale study of type 2 diabetes patients found that the use of glucagon-like peptide-1 (GLP-1) receptor agonists and inhibitors of the GLP-1 degrading enzyme dipeptidyl peptidase 4 (DPP-4) significantly reduced the incidence of PD." (PMID 38918434, 2024). "The present study aimed to evaluate the effect of DPP-4 inhibitors on sMMSE scores, serum BDNF, and PTX-3 levels in patients with type 2 diabetes, compared with patients who only use metformin treatment." (PMID 38510866, 2024). "Two classes of drugs, DPP-4 inhibitors and GLP-1 agonists target this pathway and are used in the treatment of type 2 diabetes, a common comorbidity in heart failure patients." (PMID 38500750, 2024).
type 2 diabetes (continued). "DPP4 is well studied for its degrading glucagon-like peptide 1 (GLP-1) and the treatment of type-2 diabetes, as well as other signaling peptides including substance P, and there are several FDA approved drugs targeting DPP4." (PMID 36516892, 2023). "The enzymes considered as the current targets for type 2 diabetes, namely, α-glucosidase (α-GLU) and dipeptidyl peptidase-4 (DPP-4), were also utilized in this investigation." (PMID 37049909, 2023). "In this context, we will intensify the structure activity relationship (SAR) DPP-4 inhibitors, synthesis, and IC50 of developed compounds for treating type-2 diabetes." (PMID 37570832, 2023). "In a 2015 study, it was found that Sitagliptin, a DPP-4 inhibitor, affected the subsets of circulating CD4 + T cells in patients with type 2 diabetes." (PMID 38065905, 2023). "Recently, the DPP-4 inhibitor alogliptin was found to block the AGE-RAGE axis, and consequently reduce albuminuria in patients with type 2 diabetes." (PMID 38258046, 2023). "The dipeptidyl peptidase-4 (DPP-4) inhibitor sitagliptin phosphate increases plasma glucagon-like peptide-1 (GLP-1) concentrations and is used to treat Type 2 diabetes." (PMID 36830597, 2023). "Sitagliptin, an important member of the dipeptidyl peptidase-4 (DPP-4) inhibitors family and has been widely used for the management of type 2 diabetes." (PMID 34964708, 2022). "Recently, dipeptidyl peptidase-4 (DPP-4, a serine protease) inhibitors have emerged as a useful tool for treating type 2 diabetes." (PMID 35290413, 2022). "DPP-4 inhibitors reduce GLP-1 inactivation by inhibiting the activity of DPP-4 and are currently used in kidney injury due to type 2 diabetes." (PMID 36249783, 2022). "Incretin drugs, including GLP-1 receptor agonists and DPP-4 inhibitors (which increase the level of active GLP-1 in vivo), are a new type of drugs for the treatment of type 2 diabetes." (PMID 36568082, 2022). "Dipeptidyl-peptidase 4 (DPP-4) inhibitors and glucagon-like peptide 1 (GLP-1) agonists, two classes of medication for the treatment of type 2 diabetes, were assessed in an experimental model of myocardial ischemia in rats." (PMID 36552578, 2022). "Dipeptidyl-peptidase IV (DPP4) inhibitors are in general well-tolerated and relatively new options in the pharmacotherapy of type 2 diabetes." (PMID 35884882, 2022). "Glucagon-like peptide-1 (GLP-1) is easily degraded by dipeptidyl peptidase-4 (DPP-4) in the human body, limiting its therapeutic effect on type II diabetes." (PMID 35745659, 2022). "Randomized clinical trials enrolling participants with type 2 diabetes were included, for which SGLT-2 inhibitors, GLP-1 agonists, and DPP-4 inhibitors were compared with either each other, or placebo or no treatment." (PMID 35421174, 2022). "This study compared dapagliflozin, a sodium-glucose co-transporter 2 inhibitor, and dipeptidyl peptidase-4 inhibitors (DPP-4i) with regard to cardiovascular (CV) event incidence and direct medical costs during type 2 diabetes treatment." (PMID 34650428, 2021). "The incretin-based drug classes, dipeptidyl peptidase 4 (DPP4) inhibitors and glucagon-like peptide-1 (GLP-1)-receptor agonists, are commonly used for treatment of type 2 diabetes." (PMID 34254177, 2021). "GLP-1 agonists and dipeptidyl peptidase-4 (DPP-4) inhibitors, which prevent degradation of endogenously secreted active GLP-1, are now used extensively in the management of type 2 diabetes to improve blood glucose control." (PMID 33923589, 2021). "Based on this concept, two kinds of incretin-based therapies, including DPP4 inhibitors and GLP-1 agonist, have been developed for the treatment of type 2 diabetes." (PMID 33514826, 2021). "In this line, DPP4 inhibitors and/or GLP-1 receptor analogs are widely used for the control of hyperglycemia in type 2 diabetes." (PMID 34068970, 2021).
type 2 diabetes (continued). "Vildagliptin, an oral anti-hyperglycemic drug included in the class of dipeptidyl peptidase-4 (DPP-4) inhibitors, is widely used for type 2 diabetes." (PMID 33588758, 2021). "Our head-to-head comparisons indicate that SGLT2 inhibitors provide similar glycemic controls compared with DPP4 inhibitors, but have better effects on body weight, SBP, ALT and eGFR changes after one-year treatment in type 2 diabetes patients." (PMID 32050968, 2020). "SGLT2 inhibitors had glucose-lowering effects comparable to those of DPP4 inhibitors but more favorable pleiotropic effects on body weight, ALT and eGFR changes, potentially improving type 2 diabetes patients’ cardio-metabolic disease risks." (PMID 32050968, 2020). "Since numerous studies have shown that the inhibition of DPP-4 elevates GLP-1/GIP levels, this approach is widely used to treat type 2 diabetes." (PMID 33328991, 2020). "Dipeptidyl peptidase-4 (DPP-4) inhibitors have been reported to play a protective role against atherosclerosis in both animal models and patients with type 2 diabetes (T2D)." (PMID 32646003, 2020). "Dipeptidyl peptidase-4 (DPP-4) inhibition has been recognized as a promising approach to develop safe and potent antidiabetic agents for the management of type 2 diabetes." (PMID 33126761, 2020). "Dipeptidyl peptidase (DPP)-4, a molecular target of DPP-4 inhibitors, which are type 2 diabetes drugs, is expressed in a variety of cell types, tissues and organs." (PMID 31991851, 2020). "Sitagliptin is dipeptidyl peptidase-4 (DPP-4) inhibitor, is used to treat diabetes mellitus type II as it increases the production of insulin and decreasing the production of glucagon by the pancreas." (PMID 32298346, 2020). "Sitagliptin (SGN), a dipeptidyl peptidase-4 (DPP-4) enzyme inhibitor, has been used for the management of glycemic control in type II diabetes mellitus." (PMID 32224875, 2020). "New glucose‐lowering therapies like DPP‐4 inhibitors, GLP‐1 receptor agonists, and SGLT‐2 inhibitors have undergone cardiovascular outcome trials (CVOTs) for type 2 diabetes (T2DM), as by the guidance of the FDA." (PMID 32704554, 2020). "However, the long-term use of DPP4 inhibitors for the treatment of type II diabetes has been debated and one study suggests that patients with type II diabetes treated with a DPP4 inhibitor do not have a higher risk of developing cancers than patients treated with a placebo or other drugs." (PMID 32498358, 2020). "Since native incretin is rapidly inactivated by dipeptidyl peptidase-4 (DPP-4), DPP-resistant GLP-1 receptor agonists (GLP-1RAs), and DPP-4 inhibitors are currently used for the treatment of type 2 diabetes as incretin-based therapy." (PMID 32098413, 2020). "For several years DPP-4 inhibitors in addition to GLP-1 analogues are of major importance in the clinical management of obesity and type 2 diabetes." (PMID 32958905, 2020). "The inhibition of DPP-4 extends the half-life of endogenous active forms of GIP and GLP-1, and lowers hyperglycemia in patients with type 2 diabetes." (PMID 33105604, 2020). "Strategies to increase the presence of GLP-1 in the blood are used in the treatment of type 2 diabetes, either by using degradation resistant GLP-1 receptor agonists, or by inhibiting DPP4 activity." (PMID 31971988, 2020). "Biological interest in the DPP-4 enzyme has heightened after the discovery and approval of highly selective DPP-4 inhibitors (agents that selectively inactivate DPP-4 and augment the incretin effect) for the treatment of type 2 diabetes." (PMID 31366085, 2019). "Given that SGLT-1 inhibition enhances GLP-1 secretion and DPP-4 inhibition prolongs endogenous GLP-1 half-life, a synergic effect on glucose control in type 2 diabetes is to be expected." (PMID 30819210, 2019). "At admission, the majority of type 2 diabetes patients taking OADs were on metformin either alone (380 [41%]) or in combination with DPP-4 inhibitors (287 [31%]), while 40 (4%) used DPP-4 inhibitors only." (PMID 31830073, 2019).
type 2 diabetes (continued). "The first clinical study with a DPP-4 inhibitor was performed with NVP DPP728 at five centers in Sweden and involved 93 patients with mild drug-naive type 2 diabetes (61 men and 32 women)." (PMID 31275243, 2019). "Incretin-based therapies including dipeptidyl peptidase-4 (DPP-4) inhibitors and glucagon like peptide-1 (GLP-1) receptor agonists are novel medications for type 2 diabetes management." (PMID 30016946, 2018). "Nevertheless, as has been described here, renoprotective effects of this DPP-4 inhibitor may be predominantly mediated by its antifibrotic actions, which would not necessarily manifest as changes in albuminuria over the short-term in patients with early type 2 diabetes." (PMID 29491123, 2018). "Selective DPP4 inhibitors are marketed for the treatment of type 2 diabetes, and—as shown by us and others—this class of drugs can abrogate the truncation of CXCL10 by DPP4 in vitro and in vivo." (PMID 30026741, 2018). "GLP-1 promotes glucose-dependent insulin secretion and satiety, and has been translated into therapies for type 2 diabetes and obesity through the development of long acting GLP-1 mimetics and inhibitors of dipeptidyl peptidase 4 (DPP4)." (PMID 29031728, 2017). "This study compared the effects of two DPP-4 inhibitors (linagliptin, gemigliptin) and an SGLT2 inhibitor (dapagliflozin) on the lipid profile in patients with type 2 diabetes." (PMID 28403877, 2017). "SGLT2 inhibitor use provided significant benefits for all-cause and cardiovascular-related mortality and morbidity in patients with type 2 diabetes, compared with both placebo and other OADs such as sulfonylureas, TZD, and DPP4 inhibitors." (PMID 28542373, 2017). "DPP4 inhibitors increase active GLP-1 and GIP, modulating pancreatic α and β-cell function, and therefore are part of the target therapeutics for type 2 diabetes." (PMID 28450900, 2017). "We investigated the effects of DPP-4 inhibitors and SGLT2 inhibitors on the lipid profile in patients with type 2 diabetes." (PMID 28403877, 2017). "Gliptins or dipeptidyl peptidase-4 (DPP-4) inhibitors are used as either monotherapy or, more frequently, as add-on therapy to other oral antidiabetic drugs in type 2 diabetes (T2DM)." (PMID 28596642, 2017). "Our observational study demonstrates that DPP-4 inhibitors and SGLT2 inhibitors have different effects on plasma lipid parameters in patients with type 2 diabetes." (PMID 28403877, 2017). "DPP-4 inhibitors and SGLT2 inhibitors are both a treatment option as monotherapy or as part of dual and triple therapy in patients with type 2 diabetes, having different effects on the lipid profile." (PMID 28403877, 2017). "Previous studies suggest that dipeptidyl peptidase-4 (DPP-4) inhibitors and sodium glucose cotransporter 2 (SGLT2) inhibitors have different effects on the lipid profile in patients with type 2 diabetes." (PMID 28403877, 2017). "Linagliptin is a dipeptidyl Peptidase-4 (DPP-4) inhibitor that inhibits the degradation of glucagon-like peptide 1 (GLP-1), and has been approved for the treatment of type 2 diabetes (T2D) in clinic." (PMID 28801559, 2017). "Inhibition of DPP-4 increases circulating GLP-1 levels and was shown to be a useful intervention in type 2 diabetic patients." (PMID 26881236, 2016). "As an example, novel and more expensive glucose-lowering drugs such as GLP-1 RAs, DPP-4 inhibitors and SGLT2 inhibitors are less often prescribed in type 2 diabetes patients with statutory compared with patients with private health insurance." (PMID 27019360, 2016). "Sitagliptin, a dipeptidyl peptidase-4 inhibitor, received approval from the US FDA in 2006 for treatment of type 2 diabetes mellitus." (PMID 27631013, 2016). "Incretin-based therapies such as dipeptidyl peptidase (DPP)-4 inhibitors and glucagon-like peptide-1 receptor agonists (GLP-1RA) are now widely used in the treatment of patients with type 2 diabetes." (PMID 27483245, 2016).
type 2 diabetes (continued). "Recently, incretin drugs such as DPP-4 inhibitors and GLP-1 mimetics have been widely approved for the treatment of type 2 diabetes." (PMID 27711199, 2016). "Glucose-lowering therapy such as GLP-1 agonists, DPP4 inhibitors, and SGLT2 inhibitors is reported to improve renal function in type 2 diabetes patients." (PMID 28090540, 2016). "Vildagliptin is a selective inhibitor of dipeptidyl peptidase-4 (DPP4) and has been demonstrated to reduce the fasting and postprandial glucose levels in patients with type 2 diabetes, possibly by inhibiting the inactivation of glucagon-like peptide-1 (GLP-1)." (PMID 25452780, 2015). "Incretin-based therapies, notably DPP4 inhibitors and GLP-1 analogs, have shown great promise in the treatment of type 2 diabetes." (PMID 26312995, 2015). "Recently, incretin-based therapies, dipeptidyl peptidase-4 inhibitors (DPP-4i) and glucagon-like peptide-1 receptor agonists (GLP-1RA), have become widely available for management of type 2 diabetes and are used especially in East Asia." (PMID 25944304, 2015). "Incretin-based therapy, including dipeptidyl peptidase–4 (DPP–4) inhibitors and glucagon-like peptide–1 receptor (GLP-1R) agonists, has become a popular treatment for type 2 diabetes." (PMID 26439622, 2015). "DPP4 resistant mimetics of these endogenous peptides such as exendin-4 and liraglutide, offer extended plasma half-life as compared to endogenous hormone and they are used therapeutically for the treatment of type 2 diabetes mellitus (T2DM)." (PMID 25180755, 2014). "We showed that not only voglibose, an alpha GI, but also sitagliptin, a DPP-4 inhibitor, improves endothelial function as assessed by FMD in patients with type 2 diabetes." (PMID 25074318, 2014). "Thus, DPP-4 inhibitors may be safe drugs for patients with type 2 diabetes." (PMID 25074318, 2014). "Several treatments for type 2 diabetes (e.g. sulfonylureas, meglitinides, glucagon-like peptide-1 [GLP-1] receptor agonists and dipeptidyl peptidase-4 [DPP-4] inhibitors) directly stimulate beta cells to increase insulin release." (PMID 24585202, 2014). "GLP-1-based therapy, which includes dipeptidyl peptidase-4 (DPP-4) inhibitors and GLP-1 receptor agonists, has become a popular treatment for patients with type 2 diabetes." (PMID 25407968, 2014). "T cell DPP-4 expression, serum soluble DPP-4, and DPP-4 activities were shown to be increased in patients with type 2 diabetes." (PMID 25140306, 2014). "The present study investigated the combined effects of the DPP-4 inhibitor vildagliptin and the ARB valsartan in a mouse model of type 2 diabetes." (PMID 24188631, 2013). "Sitagliptin is an oral medication indicated for type 2 diabetes mellitus (T2DM) and prevents inactivation of GLP-1 by selectively inhibiting DPP-4, thus increasing insulin secretion and decreasing glucagon concentration in a glucose-dependent manner." (PMID 23056044, 2012). "DPP-4 inhibitors are enzyme inhibitors that inhibit the enzyme DPP-4 and are a potent treatment for type 2 diabetes." (PMID 23554750, 2012). "In fact, pioglitazone can slow down the progression to type 2 diabetes when used in IGT patient, while both GLP-1 mimetics and DPP-4 inhibitors improve β-cell function measured by HOMA-β." (PMID 22577575, 2012). "Novel incretin-based drugs, such as glucagon-like peptide-1 receptor agonists (GLP-1 RA) and dipeptidyl peptidase-4 inhibitors (DPP-4i), have been last introduced in the pharmacological treatment of type 2 diabetes." (PMID 22761607, 2012). "Novel drugs based on the incretin system, such as, glucagon-like peptide-1 receptor agonists (GLP-1 RA) and dipeptidyl peptidase-4 inhibitors (DPP-4i), have been approved for the therapy of type 2 diabetes." (PMID 22761607, 2012). "In the present study, a strong correlation was identified between PYY mRNA and DPP-4 expression in patients with obesity, both with and without type 2 diabetes." (PMID 40142315, 2025).